EGFR (epidermal growth factor receptor)
Diseases named in the same sentence as EGFR in open-access papers (continued):
Sharing a sentence is not in itself a finding about the gene and the disease.
colon carcinoma (continued). "This is exemplified by resistance to anti-EGFR therapies in colon cancer, which can be mediated by downstream KRAS- or NRAS-activating mutations." (PMID 35625759, 2022). "Sulindac metabolites – sulindac sulfide (SS) and sulindac sulfone (SF) – also downregulate EGFR activation and/or expression in cancer cells, leading to attenuation of EGFR signaling in colon cancer cells." (PMID 35874714, 2022). "Again, Ephexin1, EGFR, and EphA2 were at significantly higher levels in lung and colon cancer tissues than in normal lung and colon tissues." (PMID 35668076, 2022). "In colon cancer, EpEX binds to EGFR and activates EGFR/ERK1/2/AKT signaling, which further promotes the RIP process." (PMID 36369033, 2022). "In space, in order to further clarify the interaction between PTPN6 and EGFR, we performed immunofluorescence detection of PTPN6 and EGFR in colon cancer cells." (PMID 35186080, 2022). "Previous study showed that C12orf59 was considered as a tumor suppressor by inhibiting downstream signals, including MAPK, PI3K/Akt and Wnt/β-Catenin, induced by EGFR activation in colon cancer." (PMID 35860553, 2022). "The BODIPY-bio-conjugates containing a 3PEG-LARLLT-peptide are promising as agents for fluorescent visualization in the near-IR range for colon cancer, super-expressing EGFR." (PMID 35209191, 2022). "Weaker associations were found between right colon tumors and other mutations, such as BRAF mutations OR = 1.939 (95% CI = [0.562, 6.698]) and RR2= 1.563 (95% CI = [1.209, 1.915]), and EGFR mutations, RR2 = 1.424 (95% CI = [1.314, 1.534])." (PMID 35681771, 2022). "Cetuximab targets EGFR and is a monoclonal antibody anti-cancer drug commonly used against neck and colon cancers in advanced disease stages to inhibit cell division and growth." (PMID 35612280, 2022). "The hu-αEGFR(ACVC)-172 ADC was also tested in another syngeneic tumor model using the MC38 colon cancer cell line stably expressing EGFR." (PMID 36442099, 2022). "Our findings suggest that R9VH36 has the potential to be an alternative remedy for treating EGFR-positive colon cancer." (PMID 35578244, 2022). "Given that, in BRAF mutated colon cancer, and glioma the combination of BRAF inhibitors with anti-EGFR agents is a promising strategy." (PMID 36686797, 2022). "Catechins from green tea extract have been reported to prevent colon cancer and hepatocellular cell carcinoma by blocking the activation of the RTKs, primarily EGFR, IGF‐ 1R, VEGFR2, and related pathways." (PMID 35421091, 2022). "DCA has been demonstrated to stimulate MAPK signaling through epidermal growth factor receptor activation and calcium signaling in HT-29 colon cancer cells." (PMID 35574393, 2022). "Anti-EGFR-targeted therapy is only recommended in left-side colon cancer combined with doublet chemotherapy, including FOLFOX, FOLFIRI, and XELOX." (PMID 35965307, 2022). "Curcumin has been demonstrated to suppress colon cancer cell development by lowering EGFR expression, which is mediated by a decrease in Egr-1 activity in Caco2 and HT29 colon cancer cells." (PMID 35530318, 2022). "Knockdown of SNX1 expression can significantly increase the phosphorylation level of epidermal growth factor receptor (EGFR) and promote colon cancer cell proliferation." (PMID 35024436, 2022). "The delivery of CPT-11-loaded DSPE-PEG 2000 targeting EGFR liposome to colon cancer cells enhanced the antitumor activity of CPT-11 in SW620 cells in vitro." (PMID 35918704, 2022). "Given that, in BRAF mutated colon cancer, the combination of BRAF inhibitors with anti-EGFR agents is a promising strategy." (PMID 36686797, 2022). "Unconjugated secondary bile acids induced M3 and EGFR expression in normal human colonic epithelial cells, therefore establishing M3 as essential in colon cancer initiation." (PMID 35565451, 2022). "Once the M3 is activated, both pathways, the EGFR-dependent and -independent, are activated with effects on colon cancer progression." (PMID 35565451, 2022).
colon carcinoma (continued). "Mechanism studies showed that PTPN6 can interact with EGFR, which is expected to be a molecular target for the treatment of colon cancer." (PMID 35186080, 2022). "A further evaluation of the EGFR-targeted LPEI-PEG-GE11 polymers was conducted in a mouse model of disseminated colon cancer liver metastases, established by intrasplenic injection of LS174T human colon cancer cells." (PMID 35503582, 2022). "used cetuximab (IMC-C225, Erbitux) as an antibody against EGFR-mAbs for EGFR-positive recurrent colon cancer." (PMID 35433432, 2022). "To explore the possibility of PDGF cross-signaling via alternative receptors in CRC, we conducted a co-immunofluorescence staining analysis of PDGF and VEGFR2 or EGFR expression in primary human colon cancer tissue samples (n = 20)." (PMID 36264073, 2022). "In colon carcinoma, for example, BRAF V600E inhibition has been shown to cause a rapid feedback activation of EGFR, which supports continued proliferation in the presence of BRAF V600E inhibition." (PMID 34630336, 2021). "In preclinical studies, gefitinib has anti-tumor activity against various human cancer cell lines expressing EGFR, including lung, ovarian, breast, and colon cancer." (PMID 33980216, 2021). "Solberg and colleagues proposed the use of G007-LK at low dosage with the PI3K (BKM120) and the epidermal growth factor receptor (EGFR) (erlotinib) inhibitors to treat colon cancer." (PMID 33910596, 2021). "Both, GFHP diet or anti-EGFR antibody treatment, improved tumor differentiation and anti-tumor immune response, resulting in an efficient reduction of colonic tumor burden." (PMID 34830971, 2021). "The authors concluded that although LPA does transactivate EGFR in colon cancer cells, EGFR-independent pathways also contribute to LPA-induced proliferation and migration." (PMID 34440828, 2021). "Competitive binding studies using three cell lines with different expressions of EGFR show that 5 binds specifically to EGFR-overexpressing colon cancer cells." (PMID 33498632, 2021). "The induction of ubiquitination and consequent lysosomal degradation of EGFR, both in vitro and in vivo, is another molecular mechanism that has been proposed to explain the anti-proliferative effect of HTyr treatment in colon cancer." (PMID 33513799, 2021). "FOXD3 knockdown activated a key signaling pathway in human colon cancer cells, EGFR-Ras-Raf-MEK-ERK." (PMID 33450835, 2021). "Treatment of athymic mice engrafted with EGFR-dependent colon cancers, including HCA-7, DLD-1, and HT-29 with Herceptin® showed tumor regression and decreased EGFR tyrosine phosphorylation in tumor cells." (PMID 33466394, 2021). "One example of this is anti-epidermal growth factor receptor therapies for wild-type KRAS colon cancer, which have demonstrated a preferential survival benefit for left-sided cancers." (PMID 34650170, 2021). "For instance, integrin-α2β1/-α5β1 interacted with epidermal growth factor receptor (EGFR) in the AR of colon cancer." (PMID 34456997, 2021). "Synthetic genistein glycosides were also observed to suppress EGFR phosphorylation and enhance the efficacy of radiotherapy in colon cancer cells." (PMID 34540820, 2021). "These EGFR ligands are considered to induce a stronger EGFR dependency in colon tumors which renders them particularly sensitive to anti-EGFR treatment." (PMID 34271981, 2021). "In colon cancer, EGFR activation of tumor endothelial cells is a crucial factor for determining the susceptibility of tumor therapy by EGFR-TKI." (PMID 34680445, 2021). "Future studies are needed to define the precise role of EGFR in TNBC and the effect of EGFR-TKI on TNBC, in comparison to the role of well-known EGFRs with activating mutations expressed on other neoplasms such as lung or colon cancers." (PMID 34021125, 2021). "Clinically, the differential efficacy of anti-EGFR therapy between the rectal and the left-sided colon tumours was proposed in the previous literature." (PMID 34188197, 2021).
colon carcinoma (continued). "Kirsten rat sarcoma viral oncogene (KRAS) is located downstream of EGFR signals, and KRAS mutations lead to its constitutive activation, which makes advanced colon cancer less responsive to anti-EGFR monoclonal antibodies such as cetuximab and panitumumab." (PMID 34221952, 2021). "The presence of KRAS mutations not only affects prognostic survival, but also predicts the responsiveness of patients with colon cancer to epidermal growth factor receptor (EGFR) signaling inhibitors." (PMID 35118074, 2021). "Anti-EGFR treatment has lower efficacy in metastatic middle/low rectal cancer than in left-sided colon cancer." (PMID 34188197, 2021). "In vitro work using the APC mutant HT-29 colon cancer cells showed a clear dose-dependent decrease in the phosphorylation status of Src (Y418) and EGFR (Y1068)." (PMID 34926717, 2021). "BDNF/TrkB signaling participates in the formation of drug resistance in HT-29 colon cancer cells through an EGFR-dependent mechanism." (PMID 35003085, 2021). "Several EGFR inhibitors were proven effective against epithelial-derived cancers, including lung, pancreatic, and colon cancers." (PMID 33806040, 2021). "SPHK1 regulates the PTK2/FAK (protein tyrosine kinase 2) pathway and activates the EGFR (epidermal growth factor receptor) pathway to confer tumour metastasis in colon cancer and oesophageal cancer." (PMID 34857818, 2021). "Increased activity of STAT3 induced by EGFR has been found in breast, prostate, lung, head, and neck, pancreatic and colon cancer." (PMID 34741044, 2021). "GL and GlucoGL significantly enhanced EGFR inhibitor erlotinib- or cisplatin (CDDP)-induced cell death in human colon cancer HCT116 cells." (PMID 34209885, 2021). "PI3K, mTOR (everolimus), and RET (regorafenib) inhibition seem to be synergistic with EGFR (cetuximab) inhibition in selected colon cancers with those activated pathways." (PMID 34885128, 2021). "KRAS wild-type colon cancer with EGFR expression greater than the median was predicted to be more resistant to Cetuximab (p < 0.0001)." (PMID 34548481, 2021). "In our study, we aimed to compare the efficacy of anti-EGFR therapy in treating metastatic middle/low rectal cancers and left-sided colon cancers." (PMID 34188197, 2021). "PAR1‐dependent intracellular phosphorylation of EGFR also induces proliferation of vascular smooth muscle cells, whereas PAR1 also promotes human colon cancer proliferation through EGFR transactivation." (PMID 33932087, 2021). "The proposed approach to treat APC mutated cancers is the use of G007-LK, LZZ-02, or RK-582 at low dosage in association with the PI3K (BKM120) and the epidermal growth factor receptor (EGFR) (erlotinib) inhibitors for colon cancer treatment." (PMID 34639169, 2021). "In recent studies, we established that CXCR4 antagonist MSX-122 (substituted pyrimidine-2-amine) blocked CXCL12-induced EGFR transactivation and colon cancer progression in azoxymethane-induced mouse model." (PMID 34298991, 2021). "Activating the EGFR signaling pathway in lung or colon cancer patients confers the sensitivity of EGFR inhibitors." (PMID 33959491, 2021). "MS4A12 also functions in modulating EGFR signalling, the main tumour-promoting factor in colon cancer, causing tumour growth and survival, whereas loss of MS4A12 protein deteriorated EGFR-dependent cell functions." (PMID 34573430, 2021). "In conclusion, the differential efficacy of anti-EGFR treatment between the middle/low rectal cancers and the left-sided colon cancers has been established." (PMID 34188197, 2021). "Within the ONCOTRACK project, drug sensitivity to the EGFR antibody cetuximab was determined in a cohort of 58 colon cancer PDX models, derived from 58 patients with primary or metastatic cancer." (PMID 34885128, 2021). "Epidermal growth factor receptor (EGFR) signaling drives the formation of many types of cancer, including colon cancer." (PMID 33515553, 2021).
colon carcinoma (continued). "The prominent role of EGFR signaling in colon cancer cell and its ability to modulate key hallmarks of cancer progression has already stimulated the development of several anti-EGFR monoclonal antibodies and receptor tyrosine kinase inhibitors." (PMID 33450835, 2021). "Among these, hydroxytyrosol was able to downregulate EGFR (epidermal growth factor receptor) expression and inhibit cell growth in both colon carcinoma cell lines and xenograft models with a mechanism that mimics the effect of the EGFR inhibitor cetuximab." (PMID 32933137, 2020). "Initially, cetuximab was used exclusively in colon cancer cases in which EGFR expression was observed in tumor cells by immunostaining, but subsequent studies showed good response rates in colon cancer cases in which EGFR expression was negative." (PMID 33383632, 2020). "To provide insights into combination treatment, we investigated the contribution of EGFR to 5-FU resistance in colon cancer." (PMID 31896739, 2020). "A recent meta-analysis found that colon cancer patients with BRAF mutations had worse overall survival (OS) and PFS following anti-EGFR therapies compared to patients with wild-type BRAF tumors." (PMID 32599843, 2020). "While miR-17 promoted, miR-145 inhibited the internalization of EGFR upon EGF binding to the plasma membrane in human colon cancer cells SW1116." (PMID 33240194, 2020). "Gandhy and colleagues found that curcumin and its synthetic analog RL197 induced ROS accumulation in colon cancer cells, which decreased expression of Sp1, Sp3, Sp4 and Sp-regulated genes, including EGFR." (PMID 35006436, 2020). "As a starting point, we used different colon cancer cell models in order to mimic the interpersonal heterogeneity with respect to the administration of anti-EGFR MoAbs." (PMID 33233823, 2020). "Presently, RAS is the only predictive biomarker in the application of anti-EGFR agents to treat wild-type colon cancer." (PMID 33254149, 2020). "While bevacizumab has previously been shown to induce tumor hypoxia, we here report that EGFR inhibition by cetuximab protects colon cancer cells from hypoxia-induced cell death." (PMID 33092032, 2020). "As a consequence, it was shown that concurrent inhibition of BRAF and EGFR strongly reduces the growth of BRAF mutant colon cancer cells, both in vitro and in vivo." (PMID 33291749, 2020). "EGFR contributed to 5-FU resistance in colon cancer cells through autophagy induction, and EGFR overexpression in 5-FU resistant colon cancer was regulated by RARA." (PMID 31896739, 2020). "The potential antitumoral of p-coumaric acid has also been demonstrated by the down-regulation and inhibition of EGFR active site in colon cancer cell lines." (PMID 32178333, 2020). "The regulatory role of EGFR in 5-FU resistance was validated in colon cancer cells in vivo and in vitro." (PMID 31896739, 2020). "RPN2 was reported to regulate colon cancer cell proliferation through mediating the glycosylation of EGFR, which affectes the EGFR/ERK signaling pathways." (PMID 32404045, 2020). "Further, a previous study of colon cancer shows activation of the EGFR signaling pathway through fibroblast growth factor receptor 4 (FGFR4), a tyrosine kinase." (PMID 33037736, 2020). "Tenfold LINC00973 transcriptional up-regulation was observed upon treatment of colon cancer cells with EGFR-inhibiting antibody cetuximab." (PMID 33171937, 2020). "EGFR refers to a family of receptor tyrosine kinases overexpressed by many types of cancer, including breast, lung, and colon cancer." (PMID 33158043, 2020). "Analysis of human colon cancer shows that DSG2 protein expression is increased and mediates the proliferation of colon cancer cells through the EGFR signaling pathway." (PMID 32997416, 2020).
colon carcinoma (continued). "AQP3 has been suggested to modulate tumor differentiation in colon cancer patients via the EGFR pathway, but its role remains to be defined." (PMID 32679804, 2020). "Blocking of EGFR endocytosis by miR-145 resulted in prolonged EGFR membrane signaling and altered responsiveness of colon cancer cells to EGFR-targeting drugs." (PMID 33240194, 2020). "Consistently, immunohistochemical staining revealed that the specimens from relapsed colon cancer exhibited higher levels of EGFR expression than adjacent tissues or untreated colon cancer tissues." (PMID 31896739, 2020). "Colon cancer is one of the cancer types with the highest prevalence, and new drug development has focused either on the anti-Epidermal Growth Factor Receptor (EGFR) or anti-Vascular Endothelial Growth Factor (VEGF) pathways." (PMID 32977434, 2020). "In colon carcinoma cells, the fibronectin/α5β1 axis overcomes the inhibition of EGFR-mediated cell growth by mAb225, the murine form of the chimeric anti-EGFR antibody cetuximab." (PMID 31109009, 2019). "While transcriptional repressor FOXD3 is expressed in many types of embryonic cells, its knockdown dramatically increases human colon cancer cell proliferation, affecting the EGFR-Ras-Raf-MEK-ERK signaling pathway." (PMID 30987631, 2019). "A recent study indicates that forkhead box D3 is a tumor suppressor of colon cancer via the inhibition of EGFR/RAS/RAF/MEK/ERK signal pathway." (PMID 30858760, 2019). "In tumors, HOXA3 is reported to promote human colon cancer formation by regulating the EGFR/Ras/Raf/MEK/ERK signaling pathway." (PMID 31615976, 2019). "A previous investigation indicated that afatinib, a pan-HER inhibitor, is effective against colon cancer cells resistant to anti-EGFR therapy." (PMID 31426807, 2019). "Recently, EpEX has been shown to serve as a soluble agonist to promote cell migration and proliferation through activation of the EGFR pathway in colon cancer." (PMID 31332522, 2019). "This study proposes a multifunctional nanoparticle formulation for targeted modulation of apoptosis/EGFR/HER/EMT/resistance/progression pathways to increase the sensitivity of colon cancer cells to afatinib." (PMID 31426807, 2019). "Previous work has shown that the anti-EGFR mAb cetuximab induces immunogenic cell death (ICD) in colon cancer cells by triggering endoplasmic reticulum stress response and CRT translocation, depending on the mutational status of the EGFR signaling pathway." (PMID 32082304, 2019). "In colon cancer this relationship is likely maintained as human CRCs frequently over-express EGFR and, as reviewed above, M3R is often similarly over-expressed." (PMID 30841571, 2019). "Plasma membrane microdomains are also known to organize transmembrane receptors such as EGFR a member of the receptor tyrosine kinase family that is overexpressed in many cancer types such as breast and colon cancers." (PMID 31477154, 2019). "We also analyzed the sensitivity of EGFR inhibitors in different sub-clusters of colon cancer cells." (PMID 31596728, 2019). "Enhanced CBL activity is known to result in the down-regulation of EGFR expression and inhibition of proliferation in colon tumor cells." (PMID 31324852, 2019). "In fact, inhibition of EGFR signaling in colon cancer cells modulates cytokines and growth factors secretion (e.g., IGF-1) and prevents M1-to-M2 macrophage polarization within the tumor, thereby inhibiting cancer cell growth." (PMID 31370270, 2019). "To investigate the functional consequences of EGFR pathway inhibition by monoclonal antibodies in cells harboring activating oncogenic RAS mutations, we explored colon cancer cell lines as a potential model system." (PMID 32039027, 2019). "The epidermal growth factor receptor (EGFR) represents an important drug target in colon cancer treatment." (PMID 31596728, 2019).